CACHD1 (cache domain containing 1)
Description:
May regulate voltage-dependent calcium channels.
Synonyms: KIAA1573; DVWS; formerly VWCD1
Tractability: Antibody: UniProt predicts a signal peptide or a membrane-spanning region. PROTAC: its protein half-life has been measured.
Gene: Protein-coding gene on chromosome 1 (64,469,765 to 64,693,058, forward strand). Ensembl gene ENSG00000158966.
Subcellular location: Membrane
Subcellular location (Human Protein Atlas): Nucleoli; Nucleoplasm
Gene Ontology:
Molecular function: channel activator activity; voltage-gated calcium channel activity; protein-macromolecule adaptor activity
Biological process: neurogenesis; positive regulation of protein localization to cell surface; calcium ion transmembrane transport
Cellular component: plasma membrane; voltage-gated calcium channel complex; membrane
Genetic constraint (gnomAD): Loss-of-function variants: 54 observed, 107.06 expected, observed/expected ratio (o/e) 0.5, 90% interval 0.4 to 0.63. The upper end of that interval is the gene's LOEUF score, 0.63, which puts it in group 2 of 6, group 1 being the genes least tolerant of losing a copy. Missense variants: 1,184 observed, 1,426.3 expected, observed/expected ratio (o/e) 0.83, 90% interval 0.79 to 0.87. Synonymous variants: 495 observed, 522.36 expected, observed/expected ratio (o/e) 0.95, 90% interval 0.88 to 1.02.
Homologues: Orthologues: chimpanzee CACHD1 (99% identical), macaque CACHD1 (99% identical), dog CACHD1 (98% identical), rabbit CACHD1 (98% identical), rat Cachd1 (97% identical), mouse Cachd1 (97% identical), guinea pig CACHD1 (94% identical), pig CACHD1 (94% identical), tropical clawed frog cachd1 (90% identical), zebrafish cachd1 (86% identical), Drosophila melanogaster CG16868 (31% identical). Paralogues in human: CACNA2D3 (19% identical), CACNA2D2 (17% identical), CACNA2D4 (17% identical), CACNA2D1 (17% identical).
Diseases named in the same sentence as CACHD1 in open-access papers:
CACHD1 is named in the same sentence as 20 diseases in open-access papers, as found by Europe PMC text mining. Sharing a sentence is not in itself a finding about the gene and the disease. The quoted sentences say what the papers report.
Alzheimer disease (1 paper, 2021). A progressive, neurodegenerative disease characterized by loss of function and death of nerve cells in several areas of the brain leading to loss of cognitive function such as memory and language. "Moreover, CACHD1 has been recently identified as a substrate of γ-secretase in CNS, which is well-known for its role in Notch signaling and in Alzheimer’s disease, where it catalyzes the formation of the pathogenic amyloid beta (Abeta) peptide, which modulates voltage-gated Ca2+ channel activity." (PMID 33802238, 2021).
astrocytoma (1 paper, 2021). "Mutations of CACHD1 gene were detected in human colorectal adenocarcinoma, malignant melanoma, astrocytoma and oligodendroglioma." (PMID 33802238, 2021).
colorectal cancer (1 paper, 2024). A primary or metastatic malignant neoplasm that affects the colon or rectum. "CACHD1/Cachd1 showed similar transcriptional responses to enhanced Wnt pathway activity as other Wnt target genes, whereas CACHD1 expression was reduced in cells derived from colorectal cancers." (PMID 38696577, 2024).
epilepsy (1 paper, 2022). A brain disorder characterized by episodes of abnormally increased neuronal discharge resulting in transient episodes of sensory or motor neurological dysfunction, or psychic dysfunction. "Considering our present findings, and that Cachd1 was identified as a modulator of CaV3 activity, it may serve as a potential target in diseases such as epilepsy and pain." (PMID 36077281, 2022).
hearing loss (1 paper, 2025). "DMGs for which gene variants were identified in association with hearing loss were also identified, including COL9A3 and SLC7A8; CACHD1 was also identified in connection to hearing loss in mice." (PMID 41159936, 2025).
hepatocellular carcinoma (1 paper, 2021). A malignant tumor that arises from hepatocytes. "In this study, we present the first evidence of CACHD1 overexpression in NASH-associated hepatomas and liver preneoplastic lesions in mice." (PMID 33802238, 2021). "From the results of proteome analysis of STAM mice hepatocellular carcinomas, significant elevation of a novel protein, cache domain-containing 1 (CACHD1) was found." (PMID 33802238, 2021).
Hyperglycemia (1 paper, 2021). An increased concentration of glucose in the blood. "CACHD1 expression is likely to be stimulated by hyperglycemia and hyperlipidemia, while its function is related to the regulation of cell proliferation, autophagy and apoptosis in response to oxidative stress." (PMID 33802238, 2021).
liver cancer (1 paper, 2021). An epithelial or non-epithelial malignant neoplasm that arises from the liver. "In vitro siRNA knockdown of CACHD1 in human Huh7 and HepG2 liver cancer cell lines resulted in significant inhibition of cell survival and proliferation." (PMID 33802238, 2021). "To further investigate the influence of CACHD1 in regulation of the cell cycle, we analyzed mRNA expression of cyclin D1 and p21WAF1/Cip1 genes in CACHD1 knockdown human liver cancer cell lines." (PMID 33802238, 2021). "The role of CACHD1 in other mice NASH models and human NASH-associated liver cancer is the subject for our further investigations." (PMID 33802238, 2021). "Effect of CACHD1 knockdown on the proteome of Huh7 and HepG2 human liver cancer cell lines were investigated by QSTAR LC-Ms/Ms, and similar alterations in protein spectra were detected in Huh7 and HepG2 cells using the si-CACHD1kn-2." (PMID 33802238, 2021).
liver tumors (1 paper, 2021). "Importantly, cellular proliferation was significantly elevated, but autophagy was likely to be suppressed in both CACHD1+ foci and liver tumors of STAM mice." (PMID 33802238, 2021).
malignant peripheral nerve sheath tumor (1 paper, 2021). Malignant peripheral nerve sheath tumor (MPNST) is a rare and often aggressive soft tissue sarcoma occurring in a wide range of anatomical sites. "Most recently, CACHD1 was found up-regulated in soft tissue sarcoma, namely, malignant peripheral nerve sheath tumor (MPNST) cells (BL1391)." (PMID 33802238, 2021).
steatosis (1 paper, 2021). Increased lipid within the cytoplasm of cells. "CACHD1 expression was low in the livers of STZ control mice, and was bound to the liver areas with steatosis." (PMID 33802238, 2021).
tumor (1 paper, 2021). "In the present STAM mouse NASH model, overexpression of the novel protein, CACHD1 was first recognized in HCCs of 18-week-old mice with the help of proteome analysis, and thereafter CACHD1+ foci and tumor formation was immunohistochemically confirmed in the livers of 10- and 18-week-old STAM mice." (PMID 33802238, 2021). "In consequence of these studies, assessment of CACHD1+ foci as an early marker of preneoplastic lesions in STAM mice NASH model could become a useful tool to analyze the effects of various potential NASH and tumor inhibitors and promoters in both short- and long-term studies." (PMID 33802238, 2021).
CACHD1 also shares sentences with these, for which no sentence is quoted: colorectal adenocarcinoma (1 paper); hyperlipidemia (1); lung adenocarcinoma (1); malignant melanoma (1); neuroblastoma (1); Non-Alcoholic Steatohepatitis (1); oligodendroglioma (1); soft tissue sarcoma (1).